ELAVL3 (ELAV like RNA binding protein 3)
Description:
RNA-binding protein that binds to AU-rich element (ARE) sequences of target mRNAs, including VEGF mRNA. May also bind poly-A tracts via RRM 3 (By similarity). May be involved in neuronal differentiation and maintenance (By similarity). Plays a role in the stabilization of GAP43 mRNA and in spatial learning (By similarity).
Synonyms: HuC; PLE21; DKFZp547J036; HUCL; MGC20653
Tractability: Small molecule: a high-quality ligand is known. PROTAC: ubiquitination databases record sites on it; its protein half-life has been measured; a small molecule that binds it is known.
Gene: Protein-coding gene on chromosome 19 (11,451,326 to 11,481,051, reverse strand). Ensembl gene ENSG00000196361.
Gene Ontology:
Molecular function: mRNA 3'-UTR AU-rich region binding; protein binding; protein-RNA adaptor activity; mRNA 3'-UTR binding; nucleic acid binding; RNA binding
Cellular component: ribonucleoprotein complex
Genetic constraint (gnomAD): Loss-of-function variants: 8 observed, 35.05 expected, observed/expected ratio (o/e) 0.23, 90% interval 0.13 to 0.41. The upper end of that interval is the gene's LOEUF score, 0.41, which puts it in group 1 of 6, group 1 being the genes least tolerant of losing a copy. Missense variants: 273 observed, 534.16 expected, observed/expected ratio (o/e) 0.51, 90% interval 0.46 to 0.56. Synonymous variants: 209 observed, 229.81 expected, observed/expected ratio (o/e) 0.91, 90% interval 0.81 to 1.02.
Homologues: Orthologues: chimpanzee ELAVL3 (100% identical), macaque ELAVL3 (100% identical), dog ELAVL3 (99% identical), mouse Elavl3 (99% identical), pig ELAVL3 (99% identical), rat Elavl3 (98% identical), zebrafish elavl3 (88% identical), tropical clawed frog elavl3 (86% identical), guinea pig ELAVL3 (73% identical). Paralogues in human: ELAVL4 (82% identical), ELAVL2 (80% identical), ELAVL1 (62% identical), RBMS3 (26% identical), RBMS2 (26% identical), RBMS1 (25% identical), PABPC1L (24% identical), PABPC4 (23% identical), PABPC1 (22% identical), PABPC3 (22% identical), SF3B4 (22% identical), SYNCRIP (22% identical), and 12 more.
Diseases named in the same sentence as ELAVL3 in open-access papers:
ELAVL3 is named in the same sentence as 42 diseases in open-access papers, as found by Europe PMC text mining. Sharing a sentence is not in itself a finding about the gene and the disease. The quoted sentences say what the papers report.
glioma (5 papers, 2014 to 2021). A benign or malignant brain and spinal cord tumor that arises from glial cells (astrocytes, oligodendrocytes, ependymal cells). "Collectively, these results conclude that downregulation of KHDRBS2, RANBP17 and ELAVL3 in glioma is indeed due to DNA methylation." (PMID 28035070, 2017). "We also validated the expression pattern of two upregulated (METTL1 and OAS1) and three downregulated genes (KHDRBS2, RANBP17 and ELAVL3) in glioma cell lines using qRT-PCR." (PMID 28035070, 2017). "In addition, the expression levels of four of these genes (ATCAY, CELF3, ELAVL3 and UGT8) were highest in normal brain tissues, and negatively correlated with glioma grades." (PMID 32091665, 2020).
small cell lung carcinoma (4 papers, 2014 to 2024). Small cell lung cancer (SCLC) is a highly aggressive malignant neoplasm, accounting for 10-15% of lung cancer cases, characterized byrapid growth, and early metastasis. "Interestingly, previous studies have reported the presence of ELAVL3 autoantibodies in sera derived from small cell lung cancer patients." (PMID 38016952, 2023). "ELAVL3 (ELAV like RNA binding protein 3), an RNA-binding protein regulating post-transcriptional gene expression, is mainly expressed in neuronal cells and found as a potential mRNA marker in small cell lung cancer patients." (PMID 37924098, 2023).
amyotrophic lateral sclerosis (3 papers, 2023 to 2025). Amyotrophic lateral sclerosis (ALS) is a neurodegenerative disease characterized by progressive muscular paralysis reflecting degeneration of motor neurons in the primary motor cortex, corticospinal tracts, brainstem and spinal cord. "For example, ELAVL2 has been linked to learning and memory formation, autism spectrum disorder and schizophrenia; ELAVL3 has been linked to amyotrophic lateral sclerosis (ALS) and cerebellar ataxia; ELAVL4 has been linked to AD and PD." (PMID 39425207, 2024). "Transcriptomic profiles of motor neurons from sporadic amyotrophic lateral sclerosis nervous systems identified Elavl3 as one of the most downregulated genes." (PMID 37697079, 2023). "Notably, proteins significantly decreased under high CE burden included canonical STMN2, ELAVL3, and KALRN, as well as kinesin proteins that are genetically associated with amyotrophic lateral sclerosis." (PMID 40501554, 2025).
Alzheimer disease (2 papers, 2023 to 2025). A progressive, neurodegenerative disease characterized by loss of function and death of nerve cells in several areas of the brain leading to loss of cognitive function such as memory and language. "Elavl3 is essential for cerebellar function and has been associated with epilepsy, while Elavl4 is linked to neurodegenerative diseases, including Parkinson’s and Alzheimer’s diseases." (PMID 40000387, 2025).
cerebellar ataxia (2 papers, 2018 to 2024). A neurological syndrome characterized by clumsy and uncoordinated movement of the limbs, trunk, and cranial muscles. "Here, we show that Elavl3−/− mice exhibit slowly progressive motor deficits leading to severe cerebellar ataxia with the progression of axonal degeneration." (PMID 29426875, 2018). "In this study, we assessed how the axons of nElavl-null Purkinje cells degenerate and Elavl3−/− mice exhibit cerebellar ataxia." (PMID 29426875, 2018). "Elavl3−/− mice exhibited slowly progressive motor deficits leading to severe cerebellar ataxia, and axons of Elavl3−/− Purkinje cells were swollen (spheroid formation), followed by the disruption of synaptic formation of axonal terminals." (PMID 29426875, 2018). "Finally, we propose Elavl3−/− mice as an advanced animal model that constantly develops slowly progressive motor deficits leading to severe cerebellar ataxia, similar to human patients." (PMID 29426875, 2018).
epilepsy (2 papers, 2013 to 2025). A brain disorder characterized by episodes of abnormally increased neuronal discharge resulting in transient episodes of sensory or motor neurological dysfunction, or psychic dysfunction. "Indeed, haploinsufficiency or heterozygous mutations in Elavl3 have been linked to spontaneous epilepsy." (PMID 40000387, 2025). "The proposed mechanism suggests that Elavl3 deficiency results in impaired selective splicing of glutaminase RNA, leading to imbalances in the glutamate network, potentially increasing susceptibility to epilepsy." (PMID 40000387, 2025). "In Elavl3 knockout mice, symptoms of epilepsy include transient clonic convulsive seizures and high-frequency neuronal electrical activity." (PMID 40000387, 2025). "This correlates with our observation that NOVA haploinsufficiency is sufficient to induce spontaneous epilepsy, an observation also made with the neuronal RNABP Elavl3 and Elavl4." (PMID 23359859, 2013).
cortical dysplasia (1 paper, 2023). "A de novo missense variant (NM_001420: c.889G > A;p.Glu297Lys) in ELAVL3 was identified in patient NJ463 with severe cortical dysplasia, thin corpus callosum, dilated lateral ventricles, simplified gyral pattern and overlapping cranial sutures." (PMID 37501076, 2023).
Hyperglycemia (1 paper, 2019). An increased concentration of glucose in the blood. "We correlate the diabetic state with hyperglycemia, lower body weight, presence of late thermal hypoalgesia, Elavl2 and Elavl3 downregulation, HuB upregulation, and HuD downregulation in comparison to control conditions." (PMID 31013625, 2019).
medulloblastoma (1 paper, 2020). A malignant, invasive embryonal neoplasm arising from the cerebellum. "Moreover, activated NK cells were positively correlated with GLI2 (p = 0.020, r = 0.318) and ELAVL3 (p = 0.020, r = 0.317) expression, and resting mastocyte cells were significantly correlated with CACNA2D1 expression (p = 0.026, r = 0.303) in SHH medulloblastomas." (PMID 32508873, 2020).
neuroblastoma (1 paper, 2016). Neuroblastoma (NB) is the most common solid, extracranial childhood tumor. "To analyze the functional consequences of nELAVL binding, we used two different loss-of-function models: Elavl3/4 KO mice and nELAVL RNAi depletion in neuroblastoma cells." (PMID 26894958, 2016).
neuroendocrine tumors (1 paper, 2023). "It is evident from these studies and our own that ELAVL3 holds promise as a potential serum biomarker for the diagnosis of neuroendocrine tumors in the future." (PMID 38016952, 2023).
prostate adenocarcinoma (1 paper, 2023). "Here, we demonstrate that the RNA-binding protein ELAVL3 is specifically upregulated in neuroendocrine prostate cancer and that overexpression of ELAVL3 alone is sufficient to induce the neuroendocrine phenotype in prostate adenocarcinoma." (PMID 38016952, 2023).
prostate carcinoma (1 paper, 2023). A carcinoma that arises from epithelial cells of the prostate gland. "We then confirmed this result in a panel of prostate cancer cells and consistently observed high basal expression of ELAVL3 in NCI-H660 as well as in the neuroendocrine-associated cell line LASCPC-01, at both the RNA and protein levels." (PMID 38016952, 2023). "In summary, our study established a critical role of ELAVL3 in maintaining the neuroendocrine phenotype of prostate cancer." (PMID 38016952, 2023). "In conclusion, our study identified ELAVL3 as a pivotal oncogenic driver in the initiation and maintenance of neuroendocrine differentiation in prostate cancer." (PMID 38016952, 2023). "Our results identify ELAVL3 as a critical regulator of neuroendocrine differentiation in prostate cancer and propose a drug repurposing strategy for targeted therapies." (PMID 38016952, 2023). "Collectively, our results suggest that ELAVL3 may be responsible for promoting neuroendocrine differentiation of prostate cancer cells by stabilizing RICTOR mRNA." (PMID 38016952, 2023). "However, our analysis found that ELAVL3 was highly expressed in NEPC through the combination of multiple RNA-seq datasets from prostate cancer patients." (PMID 38016952, 2023). "Owing to the high protein sequence homology between ELAVL1 and ELAVL3, we reasonably expected that PP may inhibit the function of ELAVL3, thereby impeding the neuroendocrine differentiation of prostate cancer cells." (PMID 38016952, 2023). "Therefore, we examined the impact of ELAVL3 overexpression in prostate cancer cell lines and discovered that it effectively stimulated the expression of neuroendocrine markers, alongside MYCN, NCAM1, and SYP when compared with vector control." (PMID 38016952, 2023). "Given that neuroendocrine features are generally considered as one of the mechanisms contributing to androgen deprivation therapy resistance, we investigated whether ELAVL3 can modulate the therapy response in prostate cancer cells." (PMID 38016952, 2023).
proteinopathies (1 paper, 2024). "Though less studied in the context of TDP-43 proteinopathies, both Kalirin (KALRN) and ELAV-like protein 3 (ELAVL3) are important for neuronal homeostasis, playing functional roles in synaptic plasticity and axonal maintenance, respectively." (PMID 38308693, 2024).
Sensory neuropathy (1 paper, 2020). Peripheral neuropathy affecting the sensory nerves. "ELAVL3 was one of neuronal-specific RNA-binding proteins (Hu antigens), which was recognized by anti-hu antibody in the serum of patients with paraneoplastic encephalomyelitis and sensory neuropathy." (PMID 32874133, 2020).
cancer (8 papers, 2012 to 2023). A tumor composed of atypical neoplastic, often pleomorphic cells that invade other tissues. "Further analysis of the transcriptome data from the Cancer Cell Line Encyclopedia also revealed a relatively higher basal level of ELAVL3 in the NEPC-derived cell line NCI-H660 than in adenocarcinoma cell lines." (PMID 38016952, 2023). "A large proportion (47 RBPs) are commonly regulated in both RSCC and LSCC with several enriched for binding among DEGs (adj p < 0.05), including RBPs previously discussed in the context of CRC such MSI2, MEX3A, IGF2BP1/3, ELVAL4, and cancers in general, such as RBM47, DKC1, CELF4, ELAVL3." (PMID 32293332, 2020). "In GBM scenario, we hypothesize that downregulation of ELAVL2, ELAVL3 and ELAVL4 may be preferred to further enhance the translation of HuR, leading to a less differentiated and highly proliferative state of cancer cells." (PMID 28035070, 2017).
tumor (7 papers, 2012 to 2025). "Immunohistochemistry analysis of these tumor sections revealed that ELAVL3 deficiency inhibited cell proliferation, induced apoptosis, and caused a lineage switch from the neuroendocrine to luminal phenotype." (PMID 38016952, 2023). "Next, we examined the requirement of ELAVL3 for tumor cell proliferation in NEPC by investigating the effect of knocking down ELAVL3 on cell viability in LASCPC-01 cells." (PMID 38016952, 2023). "We observed elevated Elavl3 expression in the tumor tissues of TKO mice, as demonstrated in both primary and metastatic sites, when compared with tumor tissues derived from DKO mice and normal prostate tissues from their non-Cre littermates." (PMID 38016952, 2023). "Unfortunately, we found ELAVL3 was down-regulated in the tumor samples, this discrepancy required further study." (PMID 32874133, 2020). "PP treatment effectively reduced Elavl3 expression in tumor samples." (PMID 38016952, 2023). "We collected tumor tissues from the mice and measured the RNA and protein levels of Elavl3." (PMID 38016952, 2023). "Additionally, our investigations demonstrated that PP disrupts the interaction between ELAVL3 and downstream mRNA, resulting in the reduction of ELAVL3-induced neuroendocrine differentiation and suppression of tumor growth." (PMID 38016952, 2023). "Furthermore, we assessed the effect of PP on tumor proliferation using EdU immunofluorescence staining and found that PP effectively reduced the EdU-positive ratio and Elavl3 expression." (PMID 38016952, 2023). "Our study found that the expression of ELAVL1 was significantly high in tumor samples, while that of other three members (ELAVL2, ELAVL3 and ELAVL4) was significantly low in tumors." (PMID 28035070, 2017).
neurodegenerative disease (4 papers, 2018 to 2025). A disorder of the central nervous system characterized by gradual and progressive loss of neural tissue and neurologic function. "Elavl3 is closely related to neurodegenerative diseases and play an important role in maintaining the axonal homeostasis of neurons." (PMID 31576243, 2019). "It is possible that axonal degeneration accompanied by dysfunction of axonal transportation, such as that observed in Elavl3−/− mice, also occurs in the human brain and triggers neurodegenerative diseases." (PMID 29426875, 2018).
neurological diseases (2 papers, 2021 to 2023). "While the recognition of the role of nELAVLs proteins in general and ELAVL3 in particular in neurological diseases has mainly focused on paraneoplastic neurological syndromes, they have also been previously implicated in ALS pathogenesis." (PMID 34618203, 2021). "Interestingly, in one control nervous system from an individual who carried an ATXN2 intermediate length repeat expansion but did not have neurological disease, we observed rare nuclear depletion of ELAVL3 and dot-like inclusions in a few neurons in the motor cortex but not spinal cord." (PMID 34618203, 2021).
adenocarcinoma (1 paper, 2023). A common cancer characterized by the presence of malignant glandular cells. "Taken together, these data suggest that, in addition to the intracellular manner, ELAVL3 can be released in EVs and induce neuroendocrine differentiation of recipient adenocarcinoma cells, thereby propagating the phenotype via an intercellular mechanism." (PMID 38016952, 2023). "Moreover, ELAVL3 is shown to be released in extracellular vesicles and induce neuroendocrine differentiation of adenocarcinoma cells via an intercellular mechanism." (PMID 38016952, 2023).
ELAVL3 also shares sentences with these, for which no sentence is quoted: diabetes (3 papers); lung carcinoma (2); neurodevelopmental disorder (2); Ataxia (1); autism (1); autism spectrum disorder (1); cardiac arrest (1); embryonal tumours (1); familial amyotrophic lateral sclerosis (1); familial hypercholesterolemia (1); frontotemporal dementia (1); infection (1); intracranial hemorrhage (1); ischemia (1); Lung neuroendocrine tumors (1); microcephaly (1); mucositis (1); oligodendroglioma (1); Parkinsonism (1); schizophrenia (1); Stroke (1); α-synucleinopathy (1).